IL2 (interleukin 2)
Diseases named in the same sentence as IL2 in open-access papers (continued):
Sharing a sentence is not in itself a finding about the gene and the disease.
tumor (continued). "The expansion of CD4+ T cells in lymphopenic hosts is accompanied by the production of IL-2, which is crucial in the regulation of CD4+CD25+ Treg cell homeostasis, anti-tumor CD8+ T cell responses and the generation of CD8+ T cell memory." (PMID 21423804, 2011). "Therefore, IL-2 may have concentration/time-dependent effects on tumor growth and cytotoxicity." (PMID 20953429, 2011). "It was reported that tumor-derived exosomes could induce specific antitumor responses when the parental tumor cells were genetically modified to express pro-inflammatory cytokines such as IL-18, IL-12, and IL-2 or when the parental tumor cells were subjected to stress conditions." (PMID 22190973, 2011). "Although γδ-TCR+ T cells are reported to have lytic activity against allogeneic tumor cells, they first require in vitro activation with isopentenyl pyrophosphate (IPP) and IL-2." (PMID 20937115, 2010). "Cells in both fractions proliferated rapidly after phosphoantigen/IL-2 stimulation, but the subset expressing CD56 uniquely possessed cytolytic activity against tumor cell targets." (PMID 20396597, 2010). "After amplification in the presence of IL2, CTL can be obtained from tumour infiltrating lymphocytes (TIL), as was done in one study." (PMID 20953324, 2010). "Similar to MIC-A/-B and ULBP1-3 membrane Hsp70 also serves as recognition structure for NK cells that have been activated by the Hsp70 peptide TKD plus IL-2 (TKD/IL-2), both on tumor cells in vitro and in tumor mouse models." (PMID 21179573, 2010). "Intradermal immunization of mice with PSA induced strong humoral and cellular immune responses of the Th 1 isotype indicated by strong expression of INF-γ and IL-2 and protected mice from challenge with PSA-expressing tumor cells." (PMID 21197271, 2010). "TRAMP mice were strongly protected against tumor development when vaccinated with PSCA-based DNA, an effect supposedly mediated by CD8+ T cells and expression of the cytokines INF-γ, TNF-α, IL-2, IL-4, and IL-15 within prostate tumors." (PMID 21197271, 2010). "CD8 T cells expanded in IL-15 have a survival advantage over IL-2 generated CD8 effector T cells and IL-15 induced central memory cells show more effective tumor control than IL-2 generated effector T cells." (PMID 20543982, 2010). "The association of high expression of genes in the Th1 immune response pathways (IL12, IL2, IFNG) with good prognosis is consistent with their putative tumor-inhibitory role." (PMID 21050467, 2010). "Carbonic Anhydrase IX is generally overexpressed in such tumours and CAIX has been proven to be a good selection criteria for response to interleukin-2-based immunotherapy." (PMID 19755989, 2009). "The authors showed that IL-2 administration inhibited tumour growth and prolonged survival and that both CD8 and CD4 lymphocytes were required for tumour regression." (PMID 19935800, 2009). "Several immunological blood parameters such as serum IL-2, INF-alpha, INF-gamma, and CD4/CD8 ratio were examined after the tumor disappearance, but all were within the normal range (data not shown)." (PMID 19830126, 2009). "It is also well known that IL-2 and IFN-γ promote tumor-reactive lymphocyte proliferation, cytotoxicity and, to some extent, cytokine secretion." (PMID 19292900, 2009). "Paracrine communications between tumour cells and endothelial cells exist to initiate, propagate and support tumour cells, and involve cross-talk between a number of chemokines, such as VEGF, IL-8 and IL-2 and their receptors." (PMID 19638977, 2009). "When stimulated in vitro with cognate peptide and IL-2, HA-specific CTLs kill HA+ CT44 tumor cells efficiently and selectively." (PMID 17957257, 2007). "Tumor-specific effector T cells from TVDLN, activated with anti-CD-3 and expanded in IL-2, were examined for the expression of mRNA for various chemokines." (PMID 18001476, 2007).
tumor (continued). "On the other hand, IL-2, IL-6, IL-8, IL-10, IFN-γ, MCP-1, MIP-1β, TNF-α and, to a lesser extent, IL-1β and IL-13 were significantly overexpressed in ER-negative tumours compared with ER-positive ones, with the greatest differences observed for IL-8 and MCP-1." (PMID 17261184, 2007). "We evaluated a panel of basal cytokines more commonly involved in the tumor control and progression (IL-1 beta, IL-6, IL-8, IL-10, IL-12, TNF-α) both in 144 healthy donors and in 55 patients affected by MRCC treated with IL-2 based regimens." (PMID 17953739, 2007). "Taken together, our results indicate that preoperative treatment with IL-2 may be a feasible, yet investigational approach to complement surgical therapy and modulate some alterations of the immune system that occur perioperatively in patients undergoing tumour nephrectomy." (PMID 17031403, 2006). "For activation and maintenance of tumour-infiltrating CD8+ T cells, CD4+ T cells play an important role by secreting cytokines such as interleukin-2, which is required for CD8+ T-cell growth and proliferation." (PMID 16421594, 2006). "Our tumour tissue analyses demonstrated only modest reduction in the number of proliferating tumour cells induced by IFN-α and IL-2, suggesting that immunotherapy reduces tumour size but has only limited effect on intrinsic tumour aggressiveness in vivo." (PMID 14760375, 2004). "Local production of high concentrations of IL-2 and IFN-alpha at the tumor site was more effective in preventing tumor growth than systemic administration in patients with metastatic renal cell carcinoma." (PMID 15329148, 2004). "High doses of IL-2 are required to sustain the growth and proliferation of PBMC-derived tumour-reactive T cells and of clonal tumour infiltrating lymphocytes that were expanded ex vivo, after their reinfusion." (PMID 14970852, 2004). "The expression of cytokines such as IL-2, IL-6 and IL-10 in NPC has been studied mainly on tumor biopsies using immunohistochemical and molecular techniques." (PMID 15450122, 2004). "In a previous study, we determined that in vitro activation of tumor-sensitized L-selectinlow precursors with anti-CD3 mAb and high concentrations of IL-2 (100 U/ml) induced rapid proliferation of CD8+ effector cells." (PMID 15566571, 2004). "We observed only modest reduction in the number of proliferating tumour cells induced by IFN-α- and IL-2-based immunotherapy." (PMID 14760375, 2004). "The most likely mechanism of tumour regression is the creation of lymphokine-activated killer cells (LAK cells) by IL-2 and subsequent destruction of the tumour by the ability of LAK cells to lyse tumour cells or to induce apoptosis directly." (PMID 14583759, 2003). "So in the setting of intratumoral IL-2 treatment, LAK cells are supposed to be activated T cells inducing apoptosis in tumour cells." (PMID 14583759, 2003). "Following IL-2 exposure, a far larger number of significant correlations were observed for the TIL from both tumour types." (PMID 12610520, 2003). "A few tumours in each group were allowed to grow considerably larger before AdB7-1/IL-2 injection, OVX+placebo 1170±60 mm3 and E2 tumours 1150±132 mm3." (PMID 12865933, 2003). "A total of 23 patients treated with low dose IL-2, IFN-α and histamine were evaluable for consecutive blood samples and tumour biopsies." (PMID 12107842, 2002). "Our results demonstrate that immune effector cells localise to sites of tumour in responding patients and that both CD4 and CD8 T-cell subsets are requisite for the response to IL-2 based immunotherapy." (PMID 12107842, 2002). "Because the IL-2 tumours have an altered host cell composition, which could affect the interpretation of radiation sensitivity as measured by clonogenic cells, we employed flow cytometric analysis to determine the proportion of tumour cells vs host cells in each tumour type." (PMID 10732769, 2000).
tumor (continued). "However, tumour cells did not secrete IL-2 detectable by immunoassays, although membrane-associated IL-2 was detectable on a proportion of these cells cultured in the absence of exogenous IL-2." (PMID 10555752, 1999). "Growth of tumour cells was also inhibited by the immunosuppressive drugs, cyclosporin A (CsA), FK506 and rapamycin (RPA), known to interfere with the IL-2 pathway in lymphocytes." (PMID 10555752, 1999). "Therapies were given in one round (IL-2, days 10-13; L-NAME, days 9-13) or in two rounds (IL-2, days 10-13 and 20-23; L-NAME, days 9-13 and days 19-23) after tumour transplantation." (PMID 8546905, 1996). "The addition on day 0 of interleukin 1 beta (IL-1 beta) to MEMNCs cultured in the presence of IL-2 was effective in promoting the growth of CD3+ CD8+ cells and augmenting the cytotoxicity against autologous tumour." (PMID 7917907, 1994). "In contrast, effectors derived from IL-2-activated cultures with excess CD3+ CD4+ cells lysed both autologous and allogeneic tumour target cells." (PMID 7917907, 1994). "We have previously reported on the efficacy of intraperitoneal (i.p.)immunotherapy with interleukin-2 (IL-2) and adoptively transferred lymphokine activated killer (LAK) cells in an i.p. murine tumour model." (PMID 3264714, 1988). "In preclinical models, an IL-2-based Trikine restrained terminal differentiation of T cells, promoted stemness, and enhanced durability of tumor control without observable toxicity." (PMID 41712697, 2026). "Its anti-tumor activity was evaluated in a CT-26 tumor-bearing mouse model through histopathology, tumor inhibition rate, immune organ indices, and serum cytokine (IFN-γ, TNF-α, IL-2) assays." (PMID 41815917, 2026). "Moreover, IL-2 can activate TME T-cells in thyroid cancer by augmenting human leukocyte antigen class I (HLA-I) molecule expression and tumor antigen presentation." (PMID 40313970, 2025). "In tumor cells nuclear ST2 binds and inhibits c-Jun, preventing IL-2 production." (PMID 41459907, 2025). "When these interventions were combined, tumor weight and volume were significantly reduced, supporting the hypothesis that simultaneous disruption of the CXCL12/CXCR4 axis and IL-2 modulation could reshape immune functionality within the TME." (PMID 40698080, 2025). "Furthermore, B7-H3 upregulation increased the production of Th1/Th2 cytokines (including TNF-α, IL-2, IL-4, IFN-γ, IL-6, and IL-10) in the TME and triggered TNF-α secretion in CRC cells, contributing to tumor growth." (PMID 40214484, 2025). "Interestingly, IL-2/JES6 alone also demonstrated considerable antitumor activity at this dose, significantly inhibiting tumor growth and completely curing 6 out of 16 mice." (PMID 40789741, 2025). "Cytokine expression analysis revealed upregulation of IL-1α, IL-2, IL-4, and TNFα and downregulation of IL-6 and IL-8 in JX14P TAMs compared to JX14P-RT TAMs, suggesting that JX14P-RT TAMs have a higher capacity for tumor-promoting inflammation." (PMID 40386422, 2025). "Moreover, previous studies had shown that B7H3 can upregulate IL-2, IL-6, IL-17, and TGF-β1 levels while diminishing IFN-γ production, and B7H3 antibodies can promote the infiltration of CD8+ T cells in the tumor microenvironment." (PMID 41291854, 2025). "Nemvaleukin increased tumor-infiltrating CD4+ and CD8+ T cells, promoted the expansion of non-regulatory T-cell populations, and significantly slowed tumor growth compared to controls and recombinant human IL-2 (rhIL-2) treatment." (PMID 40636453, 2025). "Further, serum cytokine levels, such as MCP-1, GM-CSF, IL-2, IL-6, IL-7 and IL-18, correlated with tumor growth independent of various treatments." (PMID 40386779, 2025). "The researchers also showed that UCB-derived CAR-T cells were capable of short-term (10 days) anti-tumor efficacy in vivo regardless of IL-2 injections." (PMID 40191201, 2025).
tumor (continued). "For instance, murine IL-2/JES6 complexes led to significant expansion of Tregs in the tumor whereas the human IL-2-based Y33 IC did not." (PMID 40789741, 2025). "Additionally, ELISA results showed elevated levels of RFA‐induced anti‐tumor cytokines, including tumor necrosis factor‐α (TNF‐α), interleukin‐2 (IL‐2), interleukin‐12 (IL‐12), and interferon‐γ (IFN‐γ)." (PMID 40956367, 2025). "These conditioned macrophages were then co-cultured with autologous non-adherent PBMCs and tumor cells in the presence of IL-2 and α-CD3/CD28 stimulation to activate T cells." (PMID 41488634, 2025). "In one particular approach, IL-2 was attached to the surface of EVs, leading to anti-cancer effects via the induction of CD8+ T cell cytotoxicity and subsequent tumor inhibition, without causing the effect on Tregs." (PMID 40006624, 2025). "In the case of CAR-19 NK-92 cells, armouring with IL-15/IL-15Rα led to enhanced in vitro proliferation (in the absence of IL-2) and in vivo tumour control compared to soluble IL-15." (PMID 41463563, 2025). "However, exposure to paclitaxel increased tumor growth and volume, which were reversed by ibuprofen that significantly modulated cytokine levels, suppressing MCP-1 and increasing TNF-α, IL-2, VEGF, and MMP-9." (PMID 40924302, 2025). "Concerning IL-2 immunocytokines combined with anti-angiogenic treatments, the critical role of the cell surface heparan sulfate proteoglycan syndecan-1 (SDC1, CD138) in neovascularization, vasculogenic mimicry (VM), and tumor progression is well established." (PMID 39852848, 2025). "To investigate whether proliferation can also be observed in patient-derived tumor-infiltrating cells, we stimulated ex vivo –isolated Vδ2 TILs within tumor tissue with either medium or ETA-067, along with the repeated addition of IL-2 (every 3 days)." (PMID 40755782, 2025). "Three weeks after tumor cell injection, two doses of PBS, anti-MSLN CAR-like NK cells, or anti-MSLN uCAR-like NK cells (1.0 × 107) were administered intraperitoneally, with rh-IL2 administered every other day." (PMID 41436559, 2025). "Upon activation of TCR and CD28, transient phosphorylation of ZAP70 and PI3K/AKT would first occur and lead to downstream cascaded activation of ERK and NF-κB, which can promote the production and secretion of IL-2 and IFN-γ by T cells to enhance anti-tumor cytotoxicity." (PMID 40276607, 2025). "Previous studies using CD25-biased IL-2 formulations have relied on TCR-restricted T cells, which often have a much higher affinity for their antigen and thus generate a much stronger anti-tumor response." (PMID 40502703, 2025). "Finally, the intratumoral injection with IL-2 and a multifunctional nanoparticle (PIC) has been reported to improve the anti-tumor response." (PMID 39852848, 2025). "In this study, we demonstrate that exosomes derived from PCa cells contribute to CD8+ T cell exhaustion via upregulating PD-1 and TIM-3 and perturbing the secretion of effector cytokines, such as IL-2, IFN-γ, TNF-α, and TGF-β, thereby reducing the tumor-killing ability of CD8+ T cells." (PMID 40681951, 2025). "Th1 cells produce IFN-γ, IL-2, and TNF-α, playing a major role in tumor immunity." (PMID 40822970, 2025). "Consistent results were achieved for all 94 paired tumour–normal samples for TNF-α and IFN-γ, for 93 paired samples for TGF-β1 and IL-1α, for 90 paired samples for IL-1β and IL-12, and for 87 paired samples for IL-2 and IL-6 expression." (PMID 41465261, 2025). "IHC staining was performed for eight cytokine proteins—TNF-α, IFN-γ, TGF-β1, IL-1α, IL-1β, IL-2, IL-6, and IL-12—in paired PeCa tumour samples and corresponding negative-margin tissue." (PMID 41465261, 2025). "In addition, tumor rechallenge in cured mice strongly stimulated Tcm cell activation, as evidenced by increased IFN-γ and IL-2 secretion in the serum." (PMID 40593710, 2025).
tumor (continued). "Under TGF-β and IL-2 signaling, the transcription factor BCL6 antagonizes PRDM1, inhibiting the transition of TPEX cells to a TEX phenotype and enhancing CD8+ T cell-mediated anti-tumor immunity during anti-PD-1 therapy." (PMID 41182407, 2025). "IL-2 and TNF-α expression presented a significant correlation with tumor stage." (PMID 40869161, 2025). "As a result of its short half-life and low tumor accumulation, systemic IL-2 therapy does not deliver the anticipated anti-tumor effects." (PMID 40821119, 2025). "When combined with activated CTLs, it upregulated CD25 and CD69 expression on effector cells, increased the secretion of IL-2, tumor necrosis factor-α (TNF-α), and IFN-γ in vitro, and significantly curbed subcutaneous tumor growth and extended the survival time of tumor-bearing mice in vivo." (PMID 41164200, 2025). "Interestingly, IL-2 levels increased significantly by 2.07-fold and 2.29-fold when ADMA-treated DC2.4 cells were exposed to EO771 or Py230 tumor antigens, respectively." (PMID 40429627, 2025). "Previous studies have demonstrated that PD-1 therapy acts by activating T cells in the tumor, whereas “No-α” IL-2 therapy promotes the proliferation of both T cells and NK cells." (PMID 40046051, 2025). "In this study, we also observed a significant reduction in tumor-infiltrating Tregs (CD4+Foxp3+ T cells) in GSDMD-deficient or DSF-treated mice, presumably due to IL-2 reduction (data not shown)." (PMID 40759573, 2025). "We then cultured the tumor cells with and without IL-2 treatment and measured the circulating CD45+ immune cells." (PMID 40805135, 2025). "Indeed, NR4A2/A1R engineered CAR T cells exhibited significantly increased expression of IFNγ, TNF and IL-2 secretion, primarily in CD8+ CAR T cells, following tumor cell coculture." (PMID 40610421, 2025). "Therefore, it is crucial to achieve sustained presence of IL-2 and an increased CD8+ T/Treg ratio at tumor sites, simultaneously reducing its systemic exposure and mitigating adverse effects." (PMID 40009662, 2025). "To test this, we first confirmed that GSDMD deficiency in T cells, and its inactivation by DSF treatment, both decreased the IL-2 levels in the TME of multiple tumor models, regardless of the presence or absence of CD8+ T cells." (PMID 40759573, 2025). "Cytokines such as IL-2 and IL-12 are traditionally incorporated to maximize effector activation and cytotoxicity, as they strongly enhance proliferation, IFN-γ production, and direct tumor lysis." (PMID 41584600, 2025). "NKG2D CAR-T cells specifically recognized NKG2DL-positive ESCC cells and secreted high levels of TNF-α, IFN-γ, IL-10, and IL-2 in overnight cocultures, while no response was observed in the absence of target tumor cells." (PMID 40510363, 2025). "CD8+ effector and tissue-resident T cells expressed numerous IL-related receptor genes; however, they lacked stimulation from IL-related cytokines such as IL-2, IL-4, IL-7, and IL-15 when comparing response states between tumor and healthy groups." (PMID 40698080, 2025). "Additionally, IL-2 has been shown to favor Treg expansion, which can inhibit CAR T anti-tumor activity." (PMID 41346587, 2025). "Consequently, we constructed pseudobulk data to decipher the relationships among IL-2 response states, STAT5 activation in Tregs, and TOX expression in CD8+ effector and tissue-resident T cells within tumor samples." (PMID 40698080, 2025). "Similarly, a biodegradable nanoparticle platform delivering IL-2, anti-CD28, Pam3CSK4, and a NOD2 agonist, was shown to stimulate endogenous tumor-infiltrating T cells and slow tumor growth." (PMID 40948803, 2025). "To test this idea, we treated CD4+ T cells with tumor tissue supernatant during their in vitro activation, and found that cleavage of GSDMD and of caspase-8 were both weakened, leading to reduced production of IL-2." (PMID 40759573, 2025).